TNF (tumor necrosis factor)
Diseases named in the same sentence as TNF in open-access papers (continued):
Sharing a sentence is not in itself a finding about the gene and the disease.
cyst (continued). "All these data suggest that only the response to E. granulosus antigens as AgB-specific triple functional IL-2+TNF-α+Th2+ cytokines and double functional TNF-α+Th2+ cytokines CD4+ T-cells associated with cyst biological activity." (PMID 26575186, 2015). "As RANKL belongs to the TNF family and TNFα has been found to exist in cyst fluid of ADPKD mice and patients, we have proposed that TNFα and RANKL regulate Id2 nuclear translocation in renal epithelial cells." (PMID 26110849, 2015). "It has been reported that cystic growthmay be due to the autocrine stimulation of cyst epithelial cellproliferation by TNF-alpha and IL-6, and the osteolytic activityof these cytokines, causing local bone loss." (PMID 17497030, 2007). "TNF-α in cyst fluid is secreted by activated macrophages and CLECs in ADPKD kidneys." (PMID 41431718, 2026). "Compared to TNF-α+TCA, UDCA+TNF-α+TCA treatment improved cyst diameter 4.3±1.4-fold, suppressed expression of the reactive phenotype markers MCP-1, Vim, IL-8, TNF-α, and TGF-β1 (48.7±3.7-, 6.1±1.1-, 3.5±0.9-, 20.1±6.1-, and 0.31±0.08-fold, respectively), and reduced LDH activity 4.1±0.5% (p<0.05)." (PMID 38407207, 2024). "In our TNF-α+TCA injury model, both norUDCA and UDCA treatments ameliorated the loss of cyst diameter associated with injury, suppressed the upregulation of cholangiocyte-reactive phenotype markers, and reduced LDH activity associated with cytotoxic effects of injury." (PMID 38407207, 2024). "Interestingly, the TNFα level was maintained low in hormonally induced cyst (vs. APF, p < 0.05), while high intergroup variation occurred in spontaneously occurred cysts." (PMID 37173342, 2023). "ELISA results showed that IL-1α and TNF-α were high inPseudomonas-positive cyst fluids, suggesting that the proinflammatory response created by macrophages might be induced in response toPseudomonas bacteria." (PMID 35538039, 2022). "Loss of self-MHC molecules or abnormal expression of MICA/B in cystic cells induced by HSPs and cyst fluid TNF-α, NK cells, NKT cells and γδ T cells might be activated and produce lots of cytokines." (PMID 35847973, 2022). "The cyst fluid TNF-α may be secreted by activated macrophages or PKD mutant cystic renal epithelial cells or both in ADPKD kidneys." (PMID 35847973, 2022). "The rationale of Smac mimicry in ADPKD therapy relies on the fact that the cystic fluid of ADPKD cysts (in both the Pkd1−/− mouse and ADPKD patients) contains high amounts of TNF-α and the cells lining the cyst also overexpress the TNF-α receptor 1, which activates TNF-α signaling." (PMID 33920158, 2021). "However, our studies of adult testis showed that TNF-JNK signaling act locally to modulate cyst cell and germ cell homeostasis upon refeeding." (PMID 32669615, 2020). "Importantly, reproduction triggers accumulation of the tumor necrosis factor (TNF) Eiger in the testis muscle to activate JNK signaling via the TNF receptor Grindelwald in the cyst cells." (PMID 31295251, 2019). "Mechanistic compensation may have evolved to arrest cyst differentiation utilizing the same TNF signal, preventing development of defective germ cells." (PMID 31295252, 2019). "It has been suggested that IL-6 and TNF-α have a local “protector” role in gross cystic disease and may be used as a marker to identify cyst type." (PMID 27293305, 2016). "The discrepancy may also reflect differing roles of LPS and TNF-α in PKD etiology; TNF-α is known to induce cystogenesis in vivo, while it is unclear whether LPS can independently stimulate cyst growth in PKD." (PMID 26666710, 2015). "TNFα levels increase in cystic kidneys in response to macrophage infiltration and thus might contribute to cyst growth and enlargement during the progression of disease." (PMID 26110849, 2015). "In addition, the roles of TNF-alpha in cyst formation and lipopolysaccharide (LPS) in renal deterioration by peritubular capillary dysfunction have been reported." (PMID 23295127, 2013).
cyst (continued). "Moreover, TNF-α contributed to cyst growth and enlargement during ADPKD progression." (PMID 41431718, 2026). "Pkd2+/- mice develop larger, more pronounced kidney cysts when treated with Tumor Necrosis Factor alpha (TNFα, an inflammatory cytokine) to induce stress as compared to wild-type littermates, whereas treatment of Pkd2+/- mice with TNFα inhibitor blocked cyst formation." (PMID 31941974, 2020). "Interestingly, the effect of TNF-α blockade on parasite damage, as reflected in the cyst wall damage scores, suggests that the inhibition of measured proinflammatory, regulatory and other molecules did not inhibit damage to cysts caused by PZQ, as was found with DEX pretreatment." (PMID 29190292, 2017). "In this study, we present for the first time that TNFα regulates the expression and nuclear translocation of Id2 in renal epithelial cells, suggesting that cyst fluid TNFα may contribute to the upregulation and increased nuclear ld2 in ADPKD kidneys and Pkd1 mutant mouse kidneys." (PMID 26110849, 2015). "Indeed, in a mouse ADPKD model, blocking TNF-α signaling inhibited cyst formation." (PMID 20587063, 2010). "Two positive feedback loops that integrate renal inflammation in cyst development were established: SMYD2/IL-6/STAT3/SMYD2 and SMYD2/TNF-α/NF-κB/SMYD2." (PMID 41431718, 2026). "Early studies have documented kidney interstitial inflammation and fibrosis in ADPKD, with pro-inflammatory molecules, namely TNF-α and MCP-1/CCL2, being present in high concentrations in the urine and cyst fluids." (PMID 39940890, 2025). "This study is the first to show that LPS, TNF-α and IL-1β increase the production and secretion of LTB4 and cyst-LTs by the pig endometrial stromal cells." (PMID 39843578, 2025). "The microphage migration inhibitory factor (MIF) also regulates the recruitment of macrophages through TNF-α and monocyte chemoattractant protein-1 (MCP-1) and promotes cyst growth in Pkd1 mutant mouse kidneys." (PMID 39456148, 2024). "These include IFN-γ, IL-6, and TNF-α, all of which have been found by others and us to be elevated in murine models of PKD or ADPKD patient cyst fluid." (PMID 36422996, 2023). "Second, we found that the progression of PKD can be influenced by the presence of inflammatory factors such as tumor necrosis factor alpha (TNF-α) and macrophage migration inhibitory factor (MIF) in the cyst fluid." (PMID 35847973, 2022). "Further, cytokines such as interferon-gamma (IFN-γ), interleukin-6 (IL-6), IL-12b, and tumor necrosis factor (TNF) are considered signatures of T. gondii infection in the CNS of mice and have been positively correlated with cyst load and behavior." (PMID 35857765, 2022). "More interestingly, we found that cyst fluid and high iron consistently upregulated the expression of IL8 and VEGFA and downregulated the expression of TNFα and CCL2 inTHP-1 cells." (PMID 36547083, 2022). "For cyst type CE3 in Year 3, levels of IL-17A, IL-8, IL-1β, MIP-1α and MIP-1β were slightly elevated relative to those in CE4 in Year 2 whereas IL-2, TNF-α, IL-1Rα and G-CSF maintained stable levels." (PMID 32171321, 2020). "We observed that both cyst load and behavior were correlated with the expression levels of interferon-gamma (IFN-γ), interleukin-12b (IL-12b), and tumor necrosis factor (TNF)." (PMID 31940479, 2020). "They narrowed down the source of the JNK activating ligand to the muscle sheath surrounding the testes, finding that the tumor necrosis factor (TNF) ligand Eiger is both necessary and sufficient to inhibit cyst cell differentiation via JNK activation." (PMID 31295252, 2019). "When OK-432 is administered locally, inflammatory cells, such as neutrophils and monocytes, infiltrate the cyst and various cytokines, including IL-6, IL-8, IFN-γ, and TNF-α, are secreted." (PMID 27144039, 2016). "In a recent study, it was shown that the inflammatory cytokine, TNF-α, negatively modulates the function of PC2 and promotes cyst formation in Pkd2+/- mice." (PMID 20587063, 2010).
cyst (continued). "TNF-α can interfere with the localization of PC2 to both the plasma membrane and primary cilia by inducing the scaffold protein RAB11 family interacting protein 2 (FIP2), which in turn facilitates cyst formation in organ cultures and Pkd2 mutant mice." (PMID 41431718, 2026). "Interestingly, we found that the treatment of mIMCD3 cells with TNF-α, which has been demonstrated to enhance cyst growth, increased the expression of SMYD3, suggesting a positive feedback loop of SMYD3/TNF-α/NF-κB/SMYD3, in a similar manner to SMYD2." (PMID 38540216, 2024). "According to our results,Pseudomonas exacerbates the pathogenesis by increasing the productions of TNF-α, IL-1α, BCL-2 and Ki-67, suggesting that this facultative anaerobic bacterium may trigger the pathogenesis of cyst formation." (PMID 35538039, 2022). "TNF-α is an apoptosis ligand and accumulates at elevated levels in ADPKD cyst fluid." (PMID 35847973, 2022). "In addition, in vivo MIF–mediated cyst growth has been referred to macrophage recruitment and the release of monocyte chemotactic protein 1 (MCP-1) and inflammatory cytokine TNF-α." (PMID 32885302, 2020). "Both LPS and TNF-α have been consistently identified in ADPKD cyst fluid, thus it is unlikely that the lack of response to LPS is related to the availability of LPS in the cyst lumen." (PMID 26666710, 2015). "Future studies could utilize collagen matrix cyst models to investigate whether PDTC inhibits cyst growth in vitro, and thereby determine whether TNF-α-induced cystogenesis is dependent on NF-κB." (PMID 26666710, 2015). "Among those cytokines, TNF-α, which is present in the cystic fluid of human ADPKD kidneys, can disrupt the localization of polycystin-2 to the plasma membrane and primary cilia through a TNF-α induced scaffold protein FIP2, to promote cyst formation in organ cultures and in Pkd2 mutant mice." (PMID 35847973, 2022). "Limitation of parasite replication and cyst formation relies on the development of a type 1 T helper (Th1) response involving secretion of IL-12 by dendritic cells and interferon-gamma (IFN-γ) and tumor necrosis factor (TNF) by T cells and natural killer (NK) cells." (PMID 21698150, 2011). "Unlike other tubular cells, the cyst-lining cells have abundant TNFR and are bathed in TNF-α-rich fluid, which is thought to fuel an autoactivating loop promoting cyst growth." (PMID 33238462, 2020). "In this study, we had not systematically investigated the effects of iron on macrophage polarization, but we found there were higher expressions of IL8 and VEGF, lower expressions of TNFα and CCL2, and no change in IL1b and IL6 in the macrophages treated with cyst fluid and iron." (PMID 36547083, 2022).
renal cell carcinoma (51 papers, 2000 to 2026). "Targeted inhibition of PI3K/Akt reactivated GSK-3β and suppressed TNF-α-associated epithelial to mesenchymal transformation in renal cell carcinoma cells." (PMID 33920379, 2021). "The higher levels of tumour necrosis factor‐alpha (TNF‐α) are associated with tumour progression and an anti‐TNF‐α monoclonal antibody has been used successfully to treat patients with renal cell carcinoma (RCC)." (PMID 27297979, 2016). "Investigations of BH in experimental models of breast and renal cell carcinoma have observed local release of tumor necrosis factor alpha (TNFα), activation of TNFα signaling pathways and inflammatory cytokines, and intratumoral infiltration of CD8+ T cells." (PMID 38346277, 2024). "In a renal cell carcinoma (RCC) model, the level of TNF-a was surprisingly correlated with the incidence risk of the cancer, the mode of growth, invasion, and metastasis." (PMID 36235818, 2022). "For instance, IL-4 and TNF-α exert synergistic effects on the PD-L1 induction in renal cell carcinoma (RCC) by activating signaling molecules, including NF-κB, IκB, and STAT6." (PMID 34088360, 2021). "TNF-α was shown to induce epithelial to mesenchymal transformation and promote tumorigenesis in a mouse model using human renal cell carcinoma cell lines." (PMID 33920379, 2021). "Enriched KEGG pathways (p < 0.05) included those involved in “Renal cell carcinoma,” “Notch signaling pathway,” and “TNF signaling pathway”." (PMID 31046669, 2019). "TNF-α induced EMT in renal cell carcinoma by suppressing E-cadherin expression and promoting Vimentin and MMP-9 protein expression." (PMID 31068208, 2019). "Other studies indicate the safety and tolerability of administering anti-TNF (etanercept or infliximab) in cancer patients affected with ovarian cancer, or renal cell carcinoma." (PMID 31417576, 2019). "TNF also increased tumorsphere formation by renal cell carcinoma cells and induced an epithelial-mesenchymal transition." (PMID 29861860, 2018). "In renal cell carcinoma, IL-4 and TNF-α synergistically induced apoptosis and cytokine production in vitro, promoting the recruitment of different immune effector cells." (PMID 28005163, 2017). "The PI3K/Akt/GSK-3β signaling pathway plays an important role in the TNF-α-induced EMT processes of in renal cell carcinomas." (PMID 28955335, 2017). "A tumor suppressor, Von Hippel-Lindau (VHL) on chromosomal 3p25 region, has been shown to suppress NF-κB pathway and enhance TNF-induced apoptosis in renal cell carcinoma (RCC)." (PMID 28029652, 2017). "The top four scoring networks were all cancer related: 1) proteoglycans in cancer (p-value = .0049), 2) Tumor necrosis factor (TNF) signaling pathway (p-value = .0053), 3) renal cell carcinoma (p-value = .0128), and 4) pathways in cancer (p-value = .0137)." (PMID 27793030, 2016). "Moreover, Jam-α downregulation has been mediated by IFN-γ and TNF-α upregulation in renal cell carcinoma." (PMID 41596343, 2026). "The RNF26/CBX7 axis modulated the TNF pathway to promote Renal cell carcinoma proliferation." (PMID 37188171, 2023). "Interestingly, the FDA’s Adverse Event Reporting System (AERS) identified another pediatric patient with renal cell carcinoma following anti-TNF treatment." (PMID 29540190, 2018). "BACKGROUND: There is clinical evidence to suggest that tumour necrosis factor-α (TNF-α) may be a therapeutic target in renal cell carcinoma (RCC)." (PMID 20842130, 2010). "A moderate correlation (R = 0.41) was observed in primary renal cell carcinoma samples; however, RCC cells have established susceptibility to TNF family‐induced apoptosis through the TNF receptors and plasma TNFα levels are a prognostic indicator for RCC." (PMID 32602581, 2020). "TNF-α may also promote EMT in human renal cell carcinoma cell lines." (PMID 28926603, 2017).
renal cell carcinoma (continued). "Sunitinib, a drug for the treatment of renal cell carcinoma, activates the NF-κB signaling pathway through the IRE1α/TRAF2/IKKβ axis of the ER stress response, enhancing the expression of IL-6, IL-8, and TNF-α." (PMID 38775480, 2024). "TNF-α stimulates the Snail-driven EMT transition and increases the stemness properties in cholangiocarcinoma and renal cell carcinoma cells." (PMID 36979874, 2023). "Moreover, renal cell carcinomas (RCC) can also interfere with the NF-kB pathway mediated expression of TNF-α by increasing P38-MAPK activity." (PMID 36045675, 2022). "TNF involvement in epithelial-to-mesenchymal transition (EMT) was also described in other cancer models including breast, lung, and renal cell carcinoma." (PMID 31417576, 2019). "TNF-α can induce EMT and promote tumorigenicity of renal cell carcinoma and increase invasion and migration activities by inhibiting E-cadherin, upregulating vimentin expression and activating MMP-9." (PMID 28955335, 2017). "In renal cell carcinomas (RCC), TNF-α induced EMT of RCC cells by repressing E-cadherin, promoting invasiveness and activating MMP9 activity." (PMID 27429011, 2016). "Relevant study also demonstrated that co-administration of targeted TNFα and nontargeted IFNγ resulted in significant synergistic tumoricidal activity in renal cell carcinoma." (PMID 27342639, 2016). "TNF-α has also been shown to induce EMT and promote renal cell carcinoma (RCC) tumorigenesis and invasiveness by suppressing E-cadherin, upregulating vimentin, and increasing MMP9 expression." (PMID 39003350, 2024). "Targeted TNFα and nontargeted IFNγ exerted additive tumoricial activity in renal cell carcinoma." (PMID 27342639, 2016). "However, the treatment of DCs with supernatant of RCC-10 (renal cell carcinoma cells), resulted in a reduction in the expression of maturation markers, but did not affect IL-10 production in response to stimulation with TNFα, IFNα and poly I:C." (PMID 22125641, 2011). "Another group could demonstrate a non-canonical activation of GLI1 in esophageal adenocarcinoma via TNF-α and subsequently mTOR/S6K1 while Zhou and colleagues could recently show that GLI1 and GLI2 are non-canonically activated via PI3K/AKT in human renal cell carcinoma." (PMID 28418873, 2017).